MAP2K3 (mitogen-activated protein kinase kinase 3)
Diseases named in the same sentence as MAP2K3 in open-access papers (continued):
Sharing a sentence is not in itself a finding about the gene and the disease.
infection (14 papers, 2007 to 2025). The state of being infected such as from the introduction of a foreign agent such as serum, vaccine, antigenic substance or organism. "Similar results were also observed in infected cells overexpressing miRNA-21 compared with control miRNA first at 7 h post infection and persisted for at least 48 h, accompanied by downregulation of MAP2K3 and dephosphorylation of downstream targets." (PMID 31585536, 2019). "The total cell lysates were harvested for immunoblotting analysis against anti-MAP2K3 antibody at 24 h post infection." (PMID 24112539, 2013). "Differential regulation of CASP8 and MAP2K3, two genes involved in the activation of MAPK14/p38, was observed, which could explain differences in the pro-inflammatory responses observed after infection with highly and less pathogenic ASFV isolates." (PMID 36298696, 2022). "We transfected si-MAP2K3 or si-C, and after 24 h of transfection we infected the HAV genotype IIIA HA11-1299 at a 0.01 multiplicity of infection (MOI) into Huh7 cells." (PMID 34299039, 2021). "MAP2K3 was upregulated significantly 1 h post CVB infection and sustained at high levels 7 h post infection, however, the expression level dropped at 12 h, which seems to be the result of high level of miRNA-21 and in line with our previous in vivo result." (PMID 31585536, 2019). "In NHBE and THP-1 cells, five mitogen-activated protein kinase (MAPK) family members (MAP2K3, MAP2K6, MAPKAPK2, MAPKAPK3, MAPKAPK5) showed decreased activity or no significant change during pH1N1 infection, and increased activity during H3N2 and H5N1 infection." (PMID 37758692, 2023).
MAP2K3 also shares sentences with these, for which no sentence is quoted: cervical cancer (10 papers); cardiac hypertrophy (8); melanoma (7); colorectal cancer (6); diabetes (5); ovarian carcinoma (5); myocardial infarct (4); osteoporosis (4); prostate carcinoma (3); renal fibrosis (3); Arthritis (2); atopic dermatitis (2); cognitive deficits (2); colorectal (2); heart (2); Hepatic steatosis (2); hypertrophy (2); myocardial ischemia (2); nasopharyngeal carcinoma (2); non-small cell lung carcinoma (2); pancreatic cancer (2); skin cutaneous melanoma (2); acne vulgaris (1); acute lymphoblastic leukemia (1); adenocarcinoma (1); adenovirus infection (1); alcohol abuse (1); Allergy (1); Angelman-like syndrome (1); Arrhythmia (1).
A further 45 diseases each share a sentence with MAP2K3 in 1 paper.